FGFR1 (fibroblast growth factor receptor 1)
Diseases named in the same sentence as FGFR1 in open-access papers (continued):
Sharing a sentence is not in itself a finding about the gene and the disease.
pilocytic astrocytoma (continued). "It is emerging however, that while these FGFR1-mutant tumors certainly can be described histologically and biologically as low grade, they are distinct from typical pilocytic astrocytoma (WHO grade I), which are predominately driven by BRAF fusions." (PMID 32085805, 2020). "Accordingly, we document examples of pilocytic astrocytomas with FGFR1 alterations located throughout the neuroaxis and belonging to each of the three different methylation classes." (PMID 32859279, 2020). "The eight patients with FGFR1-altered LGNET with DNA methylation profiles aligning to pilocytic astrocytoma ranged from 10 to 72 years of age at time of initial diagnosis (median 17 years) and included 6 males and 2 females." (PMID 32859279, 2020). "The low grade glial or glioneuronal tumor cohort comprised samples with BRAF or FGFR1 gene alterations and included 11 dysembryoplastic neuroepithelial tumors, seven pilocytic astrocytomas, and two gangliogliomas." (PMID 33282733, 2020). "Duplication of the FGFR1 TKD has also been reported in low-grade astrocytomas more suggestive of other specific histologic entities including pilocytic astrocytoma (typically extracerebellar) and dysembryoplastic neuroepithelial tumor (DNET)." (PMID 32085805, 2020). "The purpose of this study was to associate FGFR1 and FGFR3 protein levels with clinical features and genetic alterations in ependymoma and pilocytic astrocytoma." (PMID 28468611, 2017). "FGFR1 partial duplication involving the tyrosine kinase domain (FGFR1 TKD) has been identified in pilocytic astrocytoma (WHO grade 1 tumor), diffuse astrocytoma (grade 2), dysembryoplastic neuroepithelial tumor (DNT) (grade 1), and diffuse low-grade glioma, MAPK pathway-altered." (PMID 41323387, 2025). "In addition, a partial response was observed in a young adult FGFR1 N546K-mutant pilocytic astrocytoma patient treated with pemigatinib, an FGFR1/2/3/4 ATP-competitive inhibitor." (PMID 37130917, 2023). "The FGFR1–TACC fusion most commonly occurs in pilocytic astrocytomas with a cystic lesion." (PMID 34572171, 2021). "As with FGFR1 mutations, FGFR1 TKD-duplication is more common in dysembryoplastic neuroepithelial tumors and other glioneuronal tumors, while FGFR1-TACC1 is more common in pilocytic astrocytoma." (PMID 32164789, 2020). "This suggests that PTPN11, which is expressed higher in pilocytic astrocytomas compared to normal tissue, may play a role in FGFR1-mutant tumors." (PMID 26525348, 2015). "Rather, the majority of FGFR1-altered LGNET are epigenetically dispersed amongst the RGNT, EVN, DNT, and three different pilocytic astrocytoma methylation clusters." (PMID 32859279, 2020). "Sporadic pilocytic astrocytoma frequently harbors somatic alterations in BRAF, with rare pilocytic astrocytomas containing alterations in FGFR1 and NTRK2." (PMID 32082673, 2020). "Additionally, a glioneuronal tumor with features of pilocytic astrocytoma and pleomorphic xanthoastrocytoma also harboring FGFR1-TKDD was reported to demonstrate focally elevated mitotic activity; molecular characterization revealed multiple additional variants of unknown significance." (PMID 32085805, 2020). "We used immunohistochemistry to detect FGFR1 and FGFR3 protein levels in ependymomas and pilocytic astrocytomas, and evaluated the relationship between protein expression levels, clinical features and selected genetic alterations." (PMID 28468611, 2017). "FGFR1 and FGFR3 expression levels were detected in ependymoma and pilocytic astrocytoma tissues using immunohistochemistry." (PMID 28468611, 2017). "This study reports variable FGFR1 and FGFR3 protein levels in ependymoma and pilocytic astrocytoma." (PMID 28468611, 2017). "Furthermore, all pilocytic astrocytomas in the study’s cohort harbored a MAPK pathway alteration, and Genome MuSiC algorithm suggested that the BRAF, FGFR1, KRAS, and NF1 were the only genes found to be most significantly mutated." (PMID 26525348, 2015).
pilocytic astrocytoma (continued). "The FGFR1 gene on chromosome 8p11.23 has emerged as a recurrently altered oncogene in a diverse spectrum of primary glial and glioneuronal tumor entities including DNT, RGNT, EVN, pilocytic astrocytoma, high-grade astrocytoma with piloid features, and H3 K27M-mutant diffuse midline glioma." (PMID 32859279, 2020). "Moreover, various FGFR1 alterations have been observed in pilocytic astrocytomas, suggesting that genetic FGFR1 alterations do not necessarily drive the development or progression of highly malignant tumors." (PMID 28468611, 2017). "In non-diffuse gliomas, FGFR1 alterations are commonly present in a subgroup of pilocytic astrocytomas that lack other typical MAPK pathway alterations, but FGFR1 and FGFR3 expression levels have not been systematically evaluated." (PMID 28468611, 2017).
diabetes (22 papers, 2012 to 2026). "After adjusting for sex, pathologic stage, diabetes, and other variables, FGFR1 amplification was associated with shorter DFS (AHR=1.72; 95%CI, 1.15-2.48; P<0.001)." (PMID 29179482, 2017). "In vivo, we demonstrated that AcSDKP reversed the diabetes-suppressed FGFR1 and P-MAP4K4 levels associated with the induction of TGFβ/smad signaling and EndMT in endothelial cells in hearts and kidneys." (PMID 28771231, 2017). "After adjustment for sex, pathologic stage, diabetes, adjuvant chemotherapy and other factors, FGFR1 amplification remained associated with significantly shorter OS (adjusted hazard ratio [AHR], 1.61; 95% CI, 1.10-2.43, P=0.004)." (PMID 29179482, 2017). "Attenuated signaling through the fibroblast growth factor receptor 1 (FGFR1) leads to diabetes in mice." (PMID 38957656, 2024). "In diabetes, the rising evidence highlights the protective implications of FGFR1 and endothelial FGFR1." (PMID 35216141, 2022). "Another study demonstrates that endothelial FGFR1 signaling is also important for endothelial cell heath in diabetic kidneys and the heart." (PMID 34451848, 2021). "Taken together, these data suggest that FGF1 treatment markedly reversed diabetes-induced hepatic oxidative stress by regulating FGFR1-AMPK pathway." (PMID 32194395, 2020). "In the hearts, AcSDKP reversed the diabetes-suppressed FGFR1 and P-MAP4K4 levels and the diabetes-induced TGFβ2 levels." (PMID 28771231, 2017). "The suppressed miR-29s in the fibrotic kidneys resulted in the elevation of IFN-γ; subsequently, synthesized IFN-γ inhibited both FGFR1- and FGFR1-dependent miR-let-7s expression levels in diabetes." (PMID 27425816, 2016). "The deletion of FGF21 was accompanied by a slight compensative up-regulation of cardiac FGFR1 mRNA under basal conditions, which was significantly amplified by diabetes in FGF21KO mice." (PMID 25823710, 2015). "Notably, both cardiomyocyte-specific FGFR1 knockout and pharmacological inhibition of FGFR1 have demonstrated significant protective effects against diabetes-induced cardiac inflammation." (PMID 40791737, 2025). "This assertion is also supported by prior studies showing that mice with dominant-negative loss of FGFR1 demonstrate abnormal β-cell differentiation, fasting, and nonfasting hyperglycemia (ie, diabetes-like phenotypes), despite being lean." (PMID 38957656, 2024). "Finally, we identified that the targets of Nintedanib, specifically Fgfr1 and Fgfr2, are indeed upregulated in individuals with hypertension and diabetes." (PMID 38144556, 2023). "In mice with STZ-induced diabetes, fasting blood glucose levels were significantly decreased after 4 weeks of treatment with JQ-R, whereas the phosphorylation level of FGFR1 and that of its intracellular substrate FRS2, as well as the protein levels of GLUT-1, were markedly increased." (PMID 35935824, 2022). "In addition, AcSDKP treatment restored the diabetes-suppressed endothelial FGFR1 and P-MAP4K4 expression." (PMID 28771231, 2017). "In addition, AcSDKP restored both diabetes-suppressed FGFR1 and P-MAP4K4 levels and induced TGFβ/smad signaling and EndMT in heart and kidney." (PMID 28771231, 2017). "Activation of fibroblast growth factor receptor 1 (FGFR1) signaling improves the metabolic health of animals and humans, while inactivation leads to diabetes in mice." (PMID 38957656, 2024). "To assess this possibility, we first evaluated the effects of JQJTT on FGFR1 and its downstream substrate FRS2 in the liver of mice with STZ-induced diabetes." (PMID 35935824, 2022). "It was observed that diabetes had significantly decreased FGF1 expression and enhanced FGFR1 expression in hippocampus when compared with those in db/m mice." (PMID 32460803, 2020). "In kidneys, AcSDKP also restored the diabetes-suppressed FGFR1 and P-MAP4K4 levels and the diabetes-induced TGFβ1 and TGFβ2 expression." (PMID 28771231, 2017).
diabetes (continued). "After Addmodule Score analysis, Fgfr1 and Fgfr2 were increased in hypertension as well as hypertension-diabetes, respectively, but no significant changes were seen in TGF-b1, TGF-b2, and TGF-b3, the targets of Pirfenidone." (PMID 38144556, 2023). "In summary, our study demonstrates that podocyte-derived FGF4 activates the FGFR1-AMPK-FOXO1 signaling pathway to mitigate oxidative stress and promote podocyte survival, thereby preserving glomerular integrity and protecting the kidney from diabetes-induced injury." (PMID 41290710, 2025).
head and neck squamous cell carcinoma (22 papers, 2015 to 2024). A squamous cell carcinoma that arises from any of the following anatomic sites: lip and oral cavity, nasal cavity, paranasal sinuses, pharynx, larynx, and salivary glands. "In head and neck squamous cell carcinomas, FGFR1 gene hyper-methylation was found at 18 of 42 CpG sites and hypo-methylation at 16 of 42 CpG sites, and FGFR1 demethylation was associated with acquired cetuximab resistance." (PMID 37993879, 2023). "The gene encoding fibroblast growth factor receptor 1 (FGFR1) is emerging as a therapeutic and prognostic biomarker in various cancer types, including head and neck squamous cell carcinoma (SCC)." (PMID 32326908, 2020). "In head and neck squamous cell carcinoma, FGFR1 amplification was significantly associated with poor prognostic factors such as higher T stage, and visceral metastasis." (PMID 29179482, 2017). "Studies have shown that FGFR1 gene amplification is present in 9.3% to 17.4% of patients with squamous head and neck cell carcinoma (HNSCC), while 11.8% of patients exhibit FGFR1 protein overexpression." (PMID 39590377, 2024). "FGFR1 shows enriched expression in head and neck squamous cell carcinoma (HNSCC) which can activate ERK1/2, p38 and c‐Jun." (PMID 34636482, 2021). "FGFR1 amplification in head and neck squamous cell carcinoma has recently been reported to be most common in the larynx." (PMID 29351293, 2018). "Recently, targeting FGFR1 has been under development for clinical use in the treatment of cancer and the FGFR1 inhibitor PD173074 induces mesenchymal-epithelial transition in head and neck squamous cell carcinoma." (PMID 26451614, 2015). "Studies have shown that FGFR1 knockout can cause ciliary shortening, IGFR1 plays an important role in ciliary elongation, and ABI2 is a tumor suppressor and a cell migration suppressor, participating in human head and neck squamous cell carcinoma." (PMID 32357862, 2020). "A weak overlap between FGFR1 amplification and FGFR1 overexpression was also described in a large cohort of head and neck squamous cell carcinoma (HNSCC) patients." (PMID 36231142, 2022). "In the present study, a meta-analysis was performed to clarify the correlation between FGFR1 and the survival outcomes of head and neck squamous cell carcinoma (HNSCC) patients." (PMID 33989301, 2021). "In addition in a panel of head and neck squamous cell carcinoma cell lines, FGFR1 mRNA and protein were better predictors of response to the FGFR inhibitor BGJ398 than FGFR1 copy number." (PMID 26905262, 2016).
acute myeloid leukemia (21 papers, 2012 to 2025). Acute myeloid leukemia (AML) is a group of neoplasms arising from precursor cells committed to the myeloid cell-line differentiation. "We chose 2cell lines derived from malignancies associated with genetically activated FGFR1(KG1a, 8p11-positive acute myeloid leukemia [AML]) and FGFR3 (RT-4, urothelialcarcinoma) that are also indications in which INCB054828 is currently beinginvestigated in phase 2 clinical trials." (PMID 32315352, 2020). "Hematologic malignancies associated with fibroblast growth factor receptor (FGFR1) abnormalities present in heterogeneous forms, including myeloproliferative neoplasm, acute myeloid leukemia (AML), T- or B-lineage lymphoblastic leukemia/lymphoma, and even mixed phenotype acute leukemia." (PMID 38730491, 2024). "FGFR1 fusions such as BCR–FGFR1 29 and FGFR1OP2‐FGFR1 30 have been found in acute myeloid leukemia and other cancers." (PMID 34114373, 2021). "It has been reported that combined FGFR1 and MET inhibition can improve treatment efficacy in vitro and in xenografts of acute myeloid leukemia models." (PMID 31963871, 2020). "Constitutively activated FGFR1 fusion proteins give rise to 8p11 myeloproliferative syndrome (EMS), also known as stem cell leukemia/lymphoma (SCLL), which can progress to acute myeloid leukemia (AML) or T-cell acute lymphoblastic leukemia lymphoma (T-ALL), dependent on the fusion partner gene." (PMID 35574218, 2022).
neuroblastoma (20 papers, 2010 to 2026). Neuroblastoma (NB) is the most common solid, extracranial childhood tumor. "In FGFR1N546K;MYCN transgenic mice, neuroblastoma developed within the first days of life, with fatal outcome within 3 weeks, reflecting the devastating clinical phenotypes of patients with FGFR1-mutant, high-risk neuroblastoma." (PMID 41678281, 2026). "Although FGFR genomic alterations are rare in pediatric neuroblastoma tumors, overexpression of FGFR1-4 is observed in tumor subsets and is associated with outcomes." (PMID 40510032, 2025). "Of note, a single case of FGFR1 ITD has also been reported in neuroblastoma where the duplicated region spans part of exon 17 encoding the kinase domain." (PMID 37130917, 2023). "Potential cancer driver mutations of FGFR1 occur in neuroblastoma (NB), a neural crest-derived pediatric tumor arising in sympathetic nervous system, but so far they have not been studied experimentally." (PMID 35488346, 2022). "Fibroblast growth factor receptor 1 (FGFR1) is recurrently mutated at p.N546 in neuroblastoma." (PMID 41678281, 2026). "FGFR1 gene was found mutated in neuroblastoma both at diagnosis and at relapse." (PMID 33381456, 2020). "Further, the median FGFR1 expression was ranked at the 61st percentile of expression in this cohort (median transcripts per million (TPM) of 16.3), indicating that FGFR1 is expressed in neuroblastoma." (PMID 33056981, 2020). "Regorafenib treatment also inhibited 13-cis-retinoic acid-induced RET phosphorylation, and led to reduced expression of FGFR1 and PDGFRβ, with incomplete inhibition of FGFR1 and PDGFRβ phosphorylation also noted in tested neuroblastoma cell lines." (PMID 32457362, 2020). "Elevated levels of phosphopeptides from FGFR1 and FGFR2 were also observed at high levels in these neuroblastoma cells and are implicated in the tumorigenesis of many human cancers, including neuroblastoma." (PMID 24349301, 2013). "Treatment with NGF also induces a similar nuclear accumulation of FGFR1 in human neuroblastoma cells." (PMID 23874817, 2013). "Our analysis highlights the importance of RET, IGF-1R/IR and FGFR1 as RTKs in neuroblastoma and suggests a methodology that can be used to identify potential novel biological therapeutic targets." (PMID 24349301, 2013). "Together, our data demonstrate that FGFR1N546K is a strong oncogenic driver in neuroblastoma associated with failure of current standard chemotherapy and suggest potential clinical benefit of FGFR-directed therapies in patients with high-risk mutant FGFR1." (PMID 41678281, 2026). "Our present multi-region sequencing study of 10 patients with neuroblastoma shows extensive spatial and temporal intratumour heterogeneity that also affected genes encoding actionable targets, such as ALK and FGFR1, thus, harbouring potential implications for therapeutic target selection." (PMID 34815394, 2021). "In cancer, a direct interaction between FGFR1 and TGFBR3 has been identified in neuroblastoma cells for which TGFBR3 expression decreases with tumor progression." (PMID 34068954, 2021). "ALK, FGFR1, RET, PDGFRA, DDR2, EGFR, and IGF1R were enriched in endosomes from two or more neuroblastoma cell lines, but there were profound differences among cell lines." (PMID 25884760, 2015). "The present study verifies that the nuclear accumulation of FGFR1 constitutes a common response to NGF in both neural crest derived rat PC12 and human neuroblastoma cells." (PMID 23874817, 2013). "Phosphopeptides from several RTK’s that are known for their oncogenic roles in other human tumors were identified in this neuroblastoma cell line, including IGF-1R/IR, FGFR1, FGFR2, Ret, and DDR2." (PMID 24349301, 2013). "Functional and pharmacological studies would likewise be beneficial to test whether FGFR1 N546K and the FGFR1 ITD we observed in one additional patient represent valid targets for kinase inhibition in neuroblastoma patients." (PMID 33056981, 2020).
neuroblastoma (continued). "Functional investigation of FGFR1 and FLRT1 signalling in SH-SY5Y neuroblastoma cells reveals that FLRT1 alone acts to induce a multi-polar phenotype whereas the combination of FLRT1 and FGFR activation, or expression of Y3F-FLRT1, acts to induce neurite outgrowth via MAPK activation." (PMID 20421966, 2010). "Moreover, by whole exome sequencing, we demonstrated that NB exo-DNA represents the entire exome and that it carries tumor-specific genetic mutations, including those occurring on known oncogenes and tumor suppressor genes in neuroblastoma (ALK, CHD5, SHANK2, PHOX2B, TERT, FGFR1, and BRAF)." (PMID 33915956, 2021). "Targeting of FGFR1 signalling is currently used in adult cancers and may represent an interesting application not yet explored in neuroblastoma." (PMID 33381456, 2020). "However, PON does not affect neuroblastoma cells through the chimeric protein BCR-ABL, since it is not found in this pediatric malignancy, but rather through other TKs, such as FGFR1 or EGFR." (PMID 32962733, 2020).